MTOR (mechanistic target of rapamycin kinase)
Diseases named in the same sentence as MTOR in open-access papers (continued):
Sharing a sentence is not in itself a finding about the gene and the disease.
lymphoma (continued). "Using steroid-induced skin atrophy as a model, we identified and validated REDD1 and FKBP51 as genes central for atrophy in skin and discovered that many PI3K/Akt/mTOR inhibitors can strongly down-regulate the expression of these atrophogenes in skin, lymphoma cells, and in osteocytes." (PMID 35198100, 2022). "Because mTOR may induce cellular growth and proliferation, mTOR inhibitors have been used therapeutically in the treatments of lymphoma, and mTOR regulatory miRNAs may have potential therapeutic applications." (PMID 34913612, 2022). "In addition, OSS-128167 is a novel SIRT6 inhibitor and presents excellent anti-lymphoma effects by inhibiting PI3K/Akt/mTOR pathway." (PMID 35915188, 2022). "SHI’s impact on the AKT/mTOR signaling pathway has also been shown in lymphoma." (PMID 35267423, 2022). "The mTOR expression was especially upregulated in thymoma and lymphoma." (PMID 35082928, 2022). "Indeed, a recent publication using MYC-driven lymphoma cell lines also demonstrated that eIF4Ai was superior to mTOR inhibitors for inhibiting MYC expression." (PMID 34398253, 2021). "The enrichment of the autoimmune milieu with an active PI3K/Akt/mTOR pathway may act synergistically with other pathways towards lymphoma development." (PMID 34948236, 2021). "Activation of the PI3K/mTOR signaling pathway is recurrent in different lymphoma types." (PMID 32276228, 2020). "However, there are plenty of preclinical data sustaining the anti-tumor activity of dual PI3K/mTOR inhibitors as single agents and in combination in lymphomas." (PMID 32033478, 2020). "PQR620 was largely cytostatic, as is the case for other mTOR inhibitors in lymphomas." (PMID 31167506, 2019). "In addition, Rictor, a key component of the mTOR complex, has been reported as a target of miR-142-3p and miR-218 in lymphoma and oral cancer cells." (PMID 30518907, 2019). "The high frequency of genomic alterations in lymphomas affecting genes coding for proteins involved in the phosphoinositide 3-kinase (PI3K)/AKT/mammalian target of rapamycin (mTOR) pathway highlights the importance of this signaling cascade as a therapeutic target." (PMID 31167506, 2019). "The mTOR pathway may be activated in lymphoma cells and its activation in patients with DLBCL is associated with unfavorable prognosis, poor response to treatment and decreased survival time." (PMID 29721185, 2018). "Moreover, the response of lymphoma to drugs such as doxorubicin and temsirolimus, a mTOR inhibitor, is significantly improves upon coadministration with metformin." (PMID 30208162, 2018). "Overall, these studies suggest a scientific rationale for combining duvelisib with a variety of agents in clinical trials targeting aggressive lymphomas, and, in particular, point to a strategy that includes agents that suppress mTOR signaling, such as dexamethasone, ibrutinib or everolimus." (PMID 30067771, 2018). "Although genetic alterations upstream of mTORC1 have been reported in different class of NH B-cell lymphomas, it might only represent a small proportion of mTOR active lymphomas." (PMID 30564554, 2018). "In this study we showed regulation of glucose uptake by c-MYC- and PI3K/AKT/mTOR dependent pathways in lymphoma cell lines and demonstrated evidence for the altered glucose metabolism as a potential target to improve inhibitor-based therapeutic approaches in these cells." (PMID 28724379, 2017). "Taken together, our results suggest that PI3K/mTOR inhibitors as well as the c-MYC inhibitor decreased the viability of lymphoma cells, reduced glucose uptake and glucose metabolism, and downregulated the expression of glycolysis-associated genes and glucose metabolism-regulating miRNAs." (PMID 28724379, 2017). "Thus, finding an overall response rate of 30% is meaningful and provides the rationale for further studies evaluating the use of mTOR as adjuvant therapy in AIDS related lymphoma, which is frequently very aggressive." (PMID 28192480, 2017).
lymphoma (continued). "In addition to Jak, PI3K, Akt, and mTOR inhibitors, we tested other drugs that have an effect on malignant lymphoma or multiple myeloma in vitro and in vivo including proteasome inhibitors, melphalan, pomalidomide, and histone deacetylase (HDAC) inhibitors." (PMID 28860565, 2017). "Because c-Myc and mTOR signaling converges at 4E-BP-1 in a c-Myc driven lymphoma mouse model, we hypothesized that a combination therapy with JQ1 and MLN0128 might augment anti-tumor effect in our disease model." (PMID 26536665, 2016). "Studies of human lymphoma cells demonstrated that inhibition of mammalian target of rapamycin (mTOR) signaling produced changes in flux through the glycolytic, pentose shunt, and TCA cycle pathways that were evident within 8 h of treatment and increased at 24 and 48 h." (PMID 27379200, 2016). "In lymphoma, overexpression of Pim kinases results in resistance to mTOR inhibitors." (PMID 26848623, 2016). "In a MYC-driven model of lymphoma, 4EBP1 is hyperphosphorylated in an mTOR-dependent manner." (PMID 25537515, 2015). "The presence of eIF4E expression by IHC should be further evaluated in trials of dual mTOR inhibitors to learn whether the expression predicts response to these agents in lymphoma patients." (PMID 25839159, 2015). "The aim of our study was to investigate mTOR activity in different lymphomas, with a focus on HL." (PMID 23693095, 2013). "The evaluation of the mTOR activity stainings of lymphoma subtypes showed high mTOR activity in the majority (>50%) of mantle cell lymphoma (11/11), Burkitt-lymphoma (6/6), diffuse large B-cell lymphoma (5/9), anaplastic large-cell lymphoma (8/9) and Hodgkin-lymphoma cases (23/23)." (PMID 23693095, 2013). "This suggests that the mTOR pathway may play an important role in the development or progression of other lymphoma types as well, and can be considered as a useful therapeutic target." (PMID 23693095, 2013). "This study examined the anti-tumor activity of the histone deacetylases (HDAC) inhibitor valproic acid (VPA) combined with the mammalian target of rapamycin (MTOR) inhibitor temsirolimus in Burkitt leukemia/lymphoma cell lines, as well as in primary tumor cells and a murine xenograft model." (PMID 23866964, 2013). "Based on our results, mTOR activity may be a potential therapeutic tool in different lymphoma types." (PMID 23693095, 2013). "The development of mTOR inhibitors has opened a new field in the clinical arena of lymphomas." (PMID 21822434, 2012). "Bortezomib (a small molecule protease inhibitor) and the mTOR inhibitors temsirolimus, everolimus, and ridaforolimus are some of the targeted therapies currently being studied in the treatment of aggressive, relapsed/refractory lymphoma." (PMID 21092307, 2010). "Since mTOR and STAT3 are constitutively active in numerous human cancers, pharmacological inhibition of these pathways are a very active area of clinical research and may be especially important in the treatment of EBV-associated lymphomas." (PMID 38612754, 2024). "Thus, pharmacologic inhibition of the PI3K/AKT/mTOR pathway can be employed for lymphoma therapy." (PMID 36982568, 2023). "However, dual pan-class PI3K/mTOR inhibitors were developed to overcome this multiple pathway issue and seem to do so in preclinical evidence, showing in vitro and in vivo preclinical antitumor activity in lymphomas as monotherapy and combination therapy." (PMID 35326659, 2022). "PI3K/Akt/mTOR activation may be an event taking place in the initial stages of a multistep process that requires further molecular and signaling alterations to induce the transition from autoimmunity to lymphoma." (PMID 34948236, 2021). "This dual blockade leads to a metabolic crisis that cannot be tolerated by lymphoma cells, which holds a promise to resolve the issues related to acquired resistance and metabolic rewiring associated with the current therapies targeting the PI3K/AKT/mTOR pathway." (PMID 32665551, 2020).
lymphoma (continued). "Indeed, since mantle cell lymphoma overexpress cyclin D1, a key protein involved in the G1/S transition phase and regulated by mTOR signalling, this lymphoma was the first hematologic disease in which the therapeutic efficiency of mTOR inhibitors was investigated." (PMID 30704144, 2019). "Other studies also revealed that inhibition of mTOR complex and enhancement of autophagy is involved in growth inhibition, apoptotic cell death in lymphoma cells, and may correlate with greater clinical outcome, suggesting a tumor-suppression role of autophagy in non-Hodgkin’s lymphoma treatment." (PMID 30027525, 2018). "Target therapy, employing proteasome inhibitors, mTOR inhibitors, tyrosine kinase inhibitors, and histone deacetylase inhibitors (HDACi), plays an important role in clinical oncology, suggesting these pathways represent key signal transductions in lymphoma tumorigenesis." (PMID 25669976, 2015). "Hence SESN1-mediated mTOR pathway inhibition may be an important mechanism of reintroducing GRag sensitivity in EZH2 mutant lymphoma cells after EPZ-6438 treatment." (PMID 25493630, 2014). "Many studies revealed that inhibition of mTOR complex and enhancement of autophagy involved in growth inhibition, apoptotic cell death in lymphoma cells and may correlates with great clinical outcome, suggesting a tumor-suppression role of autophagy in Non-Hodgkin’s lymphoma treatment." (PMID 24015249, 2013). "However, the pathological characterization of mTOR activity in lymphomas is still incomplete." (PMID 23693095, 2013). "Targeting mTOR activity may be a potential therapeutic tool in lymphomas." (PMID 23693095, 2013). "In particular, the study of lymphoma in dogs offers insight into the efficacy of inhibitors targeting key pathways like NF-κB and PI3K/Akt/mTOR and how immunotherapies such as monoclonal antibodies and CAR-T cell treatments can be adapted for veterinary use." (PMID 40002191, 2025). "We show that IL4 treatment induced RRAGD expression, that RRAGD is required for mTOR activation in lymphoma cells and that IL4-enhanced BCR signaling induced mTOR activation." (PMID 39910284, 2025). "The region encompasses the coding sequences of MTOR, TNFRSF8 (CD30), and TNFRSF1B, which are described to have an activating role in a majority of other lymphomas, potentially suggesting a pleiotropic effect of these genes in lymphomagenesis." (PMID 38460675, 2024). "By using the bioinformatics analysis, it was observed that the MTOR gene was mainly enriched in the PI3K/AKT/mTOR, MTORC1, TGF-β, and G2/M Checkpoint signaling pathway in the lymphoma database." (PMID 39054516, 2024). "Several pro-survival and oncogenic pathways, such as, for example, STAT3 and PI3K/AKT/mTOR, can be activated by KSHV proteins, making this lymphoma particularly aggressive and difficult to treat." (PMID 39339966, 2024). "The cardamonin-induced decrease in Raptor expression further disrupted the formation of the mTOR-activating complex and led to a more efficient inhibition of RRAGC-mutant lymphomas." (PMID 37749558, 2023). "The combined treatment with AZD8186 and the mTOR inhibitor AZD2014 overcame resistance to PI3Kβ/δ inhibition and completely prevented outgrowth of lymphoma cells in vivo in cell line- and patient-derived xenograft mouse models." (PMID 36352190, 2023). "For instance, a clinical mTOR inhibitor, blocking mTOR-dependent 4E-BP1 phosphorylation in human lymphomas, confers such synthetic lethality with MYC, demonstrating that MYC can become better druggable by applying this principle." (PMID 36969025, 2023).
lymphoma (continued). "One of these drugs, BEZ235 (dactolisib), showed efficacy on preclinical models of MYC‐driven lymphoma, mediated by inhibition of the DNA damage response kinase ATM along with mTOR." (PMID 36214609, 2022). "In lymphoma cells, PRDM15 regulates the transcription of key genes involved in two major metabolic axes required for tumor cell survival: PI3K/AKT/mTOR signaling (InsR and Igf1R) and glycolysis (e.g Pkm, Pfkp, Eno3)." (PMID 32665551, 2020). "In lymphoma cells, HDAC inhibition by VPA is essential for the autophagy-enhancing effects observed when it is used in combination with the mTOR inhibitor temsirolimus." (PMID 28279189, 2017). "A similar combination of everolimus, an mTOR inhibitor, and panobinostat, a pan-HDAC inhibitor, was evaluated in a phase I clinical trial in patients with lymphoma, including Hodgkin lymphoma." (PMID 27589687, 2016). "We observed that feeding lymphoma-bearing mice with a Low CHO diet resulted in AMPK activation, mTOR and eEF2 inhibition indicating a block in protein translation." (PMID 27689327, 2016). "We observed a specific synergistic effect of combining ALK inhibitors with an mTOR inhibitor (temsirolimus), in ALK+ lymphoma cells." (PMID 27662658, 2016). "Taken together, these results indicate that the Mcl-1 decrease observed in vivo in lymphoma-bearing mice fed with a Low CHO diet is mediated, at least in part, by the AMPK/mTOR control of its translation." (PMID 27689327, 2016). "Within the PI3K/mTOR pathway, combination PI3K and mTOR inhibitors have been used for the treatment of lymphomas." (PMID 26121028, 2015). "mTOR activity was estimated by immunohistochemistry (IHC) with antibodies against the active form of mTOR and its target proteins on tissue microarray (TMA) sections representing different lymphomas." (PMID 23693095, 2013). "Given MTOR’s central role in regulating cell proliferation and survival, such an interaction profile supports the potential utility of DMBP in modulating this critical signaling pathway in lymphoma." (PMID 40699833, 2025). "The constitutive activation of mTOR by LMP2A and enhanced ATP production may contribute to chemotherapeutic resistance of EBV-related lymphomas." (PMID 38612754, 2024). "Moreover, we found that the MTOR gene was mainly enriched in the PI3K/AKT/mTOR, MTORC1, and TGF-β, G2/M Checkpoint signaling pathway in the lymphoma database." (PMID 39054516, 2024). "In contrast to its effects on lymphoma cells, mTOR inhibition did not ameliorate the acquisition of cardiac phenotypes in RRAGC-mutant cardiomyopathy." (PMID 37749558, 2023). "Since cardamonin exerted an inhibitory effect on mTOR, we speculated that RRAGC-mutant lymphoma cells were selectively sensitive to cardamonin." (PMID 37749558, 2023). "In a transgenic model of MYC‐driven lymphoma, tumor initiation and maintenance were hampered by the mTOR inhibitor everolimus, albeit without suppressing MYC level and activity." (PMID 36214609, 2022). "Accordingly, simultaneous inhibition of the mTOR pathway and CDK6 activity by palbociclib exerted greater antitumor activity than either treatment alone, both in vitro in human T cell acute lymphoblastic leukemia/lymphoma and in vivo." (PMID 34439268, 2021). "In the last years, the increased understanding of MCL cell biology led to the use of different therapeutic agents active against this lymphoma, including the proteasome inhibitor bortezomib (BTZ), or mammalian target of rapamycin (mTOR) antagonists such as everolimus and temsirolimus." (PMID 27248824, 2016).
lymphoma (continued). "Consistent results were obtained in experiments performed in several B-lymphoblastoid cell lines derived from a healthy patient, suggesting that both lymphoma cells and normal lymphocytes respond in a similar way to EtOH and INK128 with respect to mTOR activity." (PMID 25849580, 2015). "The PI3K/Akt/mTOR signaling pathway, which is a master regulator of growth and survival in normal and malignant cells, is downstream of the JAK/STAT pathway and is upregulated in many types of lymphoma, including ENKTL, where it is driven by EBV infection and LMP1." (PMID 36900160, 2023). "The data indicate that without IL-6, the Eμ-myc lymphomas are more dependent on the mTOR pathway." (PMID 33651821, 2021). "We also detected changes in the expression of proteins involved in the proliferation-related mTOR and NF-κB pathways, such as LAMTOR1 and NFKBID, which was consistent with a previous study describing a multiprotein supercomplex involved in the control of oncogenic signaling in lymphoma." (PMID 32546241, 2020). "Regarding the analyzed cases of other lymphoma types, no or only low (0/+) mTOR activity was detected in marginal zone lymphomas, chronic lymphoid leukemias/small lymphocytic lymphomas and peripheral T-cell lymphomas (8/12, 12/13 and 10/12 negative/low, respectively)." (PMID 23693095, 2013). "The demonstrated activity of bortezomib in MCL, and the mTOR inhibitors everolimus and temsirolimus in DLBCL and MCL, suggests that these agents may one day have a place in the treatment armamentarium for aggressive lymphomas." (PMID 21092307, 2010). "The mTOR inhibitors everolimus (Afinitor®) and temsirolimus (Torisel®) are currently under clinical investigation for the treatment of NHL and HL, and ridaforolimus (formerly deforolimus) is being evaluated in patients with hematological malignancies including lymphoma." (PMID 21092307, 2010). "Metformin has a beneficial role in human lymphoma by inhibiting mTOR signaling without the involvement of AKT, and the suppression of mTOR subsequently leads to the suppression of growth of B cells and T cells." (PMID 32425881, 2020). "The need for alternatives to mTOR inhibitors in lymphoma is further supported by a recent paper indicating that not all lymphoma-derived cell lines express 4E-BP1 and that lymphoma cells lacking 4E-BP1 are resistant to mTOR inhibitors." (PMID 25594050, 2014). "In this tumor, the PI3K/AKT/mTOR pathway is downstream of ALK and constitutively active, but its inhibition alone might not be enough to efficiently target the lymphoma cells." (PMID 31167506, 2019).